SMAD4 (SMAD family member 4)
Diseases named in the same sentence as SMAD4 in open-access papers (continued):
Sharing a sentence is not in itself a finding about the gene and the disease.
tumor (continued). "In transgenic Apc+/∆716/Smad4+/- compound knockout mice that develop CRC, CCL9 is secreted from cancer cells, which recruits CCR1+ myeloid cells to promote tumor invasion." (PMID 38750114, 2024). "Research on SMAD4 emphasizes its regulatory role in the development of CRC, particularly with respect to the tumor microenvironment and the interactions between tumor cells and their environment." (PMID 39164192, 2024). "characterizes the tumor microenvironment in relation to carcinogenesis, and the predominant role of TGF-ß/SMAD4 signaling in cancer." (PMID 39882243, 2024). "SMAD4 is an effector downstream of the TGF‐β receptor and can respond with high sensitivity to TGF‐β and other cytokines in the tumor microenvironment." (PMID 39713206, 2024). "The KDM3A/KLF5/SMAD4/EGFR axis coordinates the regulatory mechanism involved in maintaining a low population of T cells within the tumor microenvironment (TME), thus driving resistance to immunotherapies." (PMID 39519018, 2024). "Other research has shown that when SMAD4/TGF-beta signaling occurs, lethal EMT is induced, and tumor suppression occurs." (PMID 39113194, 2024). "To test the relative importance of the STAT3 and TGF-β pathways to tumor morphology and functionality, we generated STAT3/SMAD4 and STAT3/TGFBR2 double knockout (DKO) cell lines." (PMID 38573819, 2024). "SMAD4 inactivation occur in around 50%–60% of patients with PDAC, indicating that SMAD4 functions as a specific tumour suppressor in PDAC." (PMID 38789418, 2024). "These macrophages express abundant TGF-β that activates SMAD4 signaling in PDAC cells and enables KRAS-independent tumor growth." (PMID 38167055, 2024). "Another possible mechanism is that Smad4 deficiency can enhance the immunogenicity of tumor cells, significantly increasing the activation level of DCs, and this activation of DCs is not affected by the expression of tumor cell antigen-presenting genes, such as β2M." (PMID 38982491, 2024). "STAT3 sustains the KRAS-dependent phenotype and tumor aggressiveness, with the potential for improved efficacy of anti-RAS drugs, whereas SMAD4 promotes KRAS independence at the expense of enhanced therapy resistance." (PMID 38573819, 2024). "In summary, we found significant CNA differences in CDKN2A, ERBB2, SMAD4, and CCNE1 between pNET and sbNET tumor samples after combined analyses of chromosomal microarrays, RNA sequencing, and fluorescence in situ hybridization data." (PMID 39062773, 2024).
tumor (continued). "To further analyze the mechanisms of the tumor inhibition ability of mRNA nano-lantern, we evaluated the expression level of Smad4, downstream transcriptional regulatory genes, MYC, VEGFC, and CXCL5 in tumor tissues by Western blot." (PMID 36894556, 2023). "By binding with SUMOylated-SMAD4, DAXX inhibits the tumor suppressive effect of transforming growth factor-β (TGF-β) signaling mediated by SMAD4, which affects the growth arrest and apoptosis of cancer cells." (PMID 36911524, 2023). "In our material, SMAD4 and RUNX3 were weakly to moderately correlated both between and within the tumor epithelial and stromal compartments (0.3 < r < 0.6)." (PMID 36900240, 2023). "In conclusion, our data first discovered circLDLRAD3 is downregulated in OSCC and verified its tumour suppressor function and mechanism in OSCC through sponging miR‐558 to regulate miR‐558/Smad4/TGF‐β axis." (PMID 37563869, 2023). "KLF5 is also a mediator of the inhibitory effects of the TGF-β signaling on cancer that TGF-β/SMAD4 signal inhibits the transcription of KLF5 that, in turn, switches Sox4 from tumor promoter to suppressor." (PMID 36761967, 2023). "Our study found that circLDLRAD3 is downregulated in OSCC and verified its tumour suppressor function and mechanism in OSCC through sponging miR‐558 to regulate miR‐558/Smad4/TGF‐β axis." (PMID 37563869, 2023). "In summary, we found that SMAD4 expression is lower in NSCLC and correlated with tumor differentiation, lymph node metastasis, TNM stage and good OS but not with the age or sex of NSCLC patients." (PMID 37478236, 2023). "In our study, we initially found evidence for a tumor suppressive role of TAp73 in PDAC cells of human origin by observing that TAp73 upregulated the basal expression of ECAD and SMAD4, while downregulating that of SNAIL." (PMID 37568607, 2023). "SMAD4 is the mediator of the TGF-b pathway, playing a tumor-suppressive role, particularly at early stages, since it induces cell cycle arrest and apoptosis and correlates negatively with tumor metastasis." (PMID 37687058, 2023). "KLF2 can inhibit the transcriptional activity of SMAD2/3 and SMAD4 in the TGF-β/SMAD pathway, improving TGF-β-induced target gene expression and inhibiting tumor growth and migration in HCC." (PMID 36761967, 2023). "SMAD4 is a pivotal transducer in the transforming growth factor-beta (TGF-β) signaling pathway and has been suggested to exert anti-tumor effects by regulating cell proliferation, differentiation, migration, and apoptosis." (PMID 37035326, 2023). "The result revealed that the mRNA expression level of SMAD4 and STING1 was significantly downregulated in eCCA tumour tissues compared to the para‐tumour tissue." (PMID 37488750, 2023). "Pancreas-specific PDX1-Cre or P48-Cre knockdown of SMAD4/DPC4 significantly promoted KRASG12D activation or PTEN inactivation, triggering tumour progression." (PMID 37685308, 2023). "The role of SMAD4, specifically during the process of BRAF-mutant tumor invasion, is less understood, partially owing to the limited number of model systems to monitor invasive behavior." (PMID 38136364, 2023). "SMAD4 has tumor suppressor activity, and, in its absence, the SMAD2/SMAD3 heterodimer mediates the oncogenic effects of TGFB by activating a SMAD4-independent signaling pathway." (PMID 37509254, 2023).
tumor (continued). "Expression of SMAD4 and STING1 were downregulated in CCA tumours and STING1 expression correlated with SMAD4 expression." (PMID 37488750, 2023). "This class of organ models highlights the importance of SMAD4/DPC4 deletion in PDAC invasion, suggesting that the invasive processes of the SMAD4/DPC4 mutant and SMAD4/DPC4 wild-type tumours differ in both morphological and molecular mechanisms." (PMID 37685308, 2023). "In the APC/SMAD4 mutant mouse model of CRC, the expression of CCL9 was found to be upregulated in the tumor epithelium and knockout of CCR1 prevented immature myeloid cell (also known as myeloid derived suppressor cells or MDSCs) accumulation at the tumor." (PMID 36982211, 2023). "Based on the data presented here, we conclude that TAp73 and SMAD4 signaling independently block basal and TGF-β1-induced ERK activation and cell migration in human PDAC-derived tumor cells." (PMID 37568607, 2023). "Because of the low expression of core TβR1/2, (p-)SMAD2 and SMAD4 proteins and the correlation with worse prognosis, TGF-β pathway most likely leads to tumour inhibitory effects in AC and therefore the use of TGF-β inhibitors would not be recommended." (PMID 35756604, 2022). "Although some tumor suppressors were identified by the KEGG analysis of our comparative proteomics, e.g., TIMP3 and SMAD4, most proteins of the cancer group in our dataset were oncogenic." (PMID 35999337, 2022). "In this study, although in a limited number of HNC samples, we confirmed the upregulation of SMAD4 mRNA in HPV-positive HNC tumours compared to HNC-negative and we show that also at protein level the expression of SMAD4 is higher in HPV-positive HNC." (PMID 35144669, 2022). "SMAD4 is a central regulator of the transforming growth factor-β (TGF-β) signaling pathway, which plays an important role in tumor development by inducing angiogenesis and immunosuppression." (PMID 36142142, 2022). "Together, these results indicated that Smad4 deletion in PDAC cells enhanced immunogenicity through: 1, increasing antigen presentation machinery molecule expression on tumor cells; 2, promoting DC activation." (PMID 35064757, 2022). "SMAD4, Rad51 and CHK1 expression was assessed in HPV-positive and HPV-negative HNC using TCGA data, a panel of 14 HNC cell lines and 8 fresh tumour tissue samples from HNC patients." (PMID 35144669, 2022). "Sunitinib inhibits tumor progression by inhibiting p-VEGFR-PI3K-AKT-YBX1-Snail, SMAD4/SMAD7, ERK1/2 and MAPK signaling pathways." (PMID 36544713, 2022). "Because of this, the correlation between SMAD4 and CA19-9 was less likely due to the bias of increased tumor staging." (PMID 35180847, 2022). "Knockdown of major TFs of the TGF-β pathway, SNAI1/2, and SMAD4, led to decreased FN1 expression, consequent EMT inhibition, and decreased tumor cell motility." (PMID 35216235, 2022).
tumor (continued). "In particular, one of the main player of the TGFβ pathway SMAD4, whose expression is usually decreased in many tumours such as HNC, has been previously shown to be upregulated in HPV-positive HNC tumours compared to HPV-negative." (PMID 35144669, 2022). "Knockdown of SMAD4 from human CRC cells enhances CXCL1 and CXCL8 expression and accumulates CXCR2+ neutrophils to CRC tumor." (PMID 35935996, 2022). "Thus, the function of Smad4 in regulating tumor immunity may be tumor type‐ and context‐dependent." (PMID 35064757, 2022). "Another transcription factor, Mothers Against Decapentaplegic Homolog 4 (SMAD4), concatenates immune cells and tumor by chemokines." (PMID 35935996, 2022). "SMAD4 is a critical mediator of TGF-β-induced growth arrest and apoptosis, which results in its role as a tumor suppressor at the early stages of cancer progression." (PMID 35151689, 2022). "Moreover, Jab1/CSN5 can induce the degradation of two important downstream molecules, Smad4 and Smad7, and affect transforming growth factor-b (TGFb) signaling which is also influenced by various factors in the tumor microenvironment, and might contribute to lymphatic and distant metastasis." (PMID 35870903, 2022). "The PPI network analysis with cancer-related terms defined six proteins: TGFBR2, TGF-alpha, FGF21, SMAD4, TGFBR1, and FZD3, most of which are involved in tumor development." (PMID 35999337, 2022). "SMAD family member 4 (SMAD4) is a downstream mediator of the TGF-β-signaling superfamily, which can play a tumor-suppressive role in colon carcinogenesis." (PMID 36230676, 2022). "To analyse the expression of proteins of interest in the PDX model, we performed IHC staining for BMP2, BMP4, SMAD4 and SHH on tumor, lung and colon tissue 28 days post treatment." (PMID 35902550, 2022). "MiR-146b-5p is involved in regulation of TGF-b signal transduction through suppressing SMAD4 in PTC and enhancing tumor metastasis through ZNRF3 targeting." (PMID 35659780, 2022). "Recently, SMAD4 was reported to be phosphorylated at Tyr95 directly by ALK to elicit TGF-β gene transcription and tumour-suppressing responses." (PMID 35508387, 2022). "This study further revealed the inhibitory effect of VPA on tumor invasion and metastasis in different cell lines of glioma cancer and the possible relationship between VPA, Smad4, and EMT." (PMID 35251569, 2022). "Recently, our study reported that the hypomethylation in the CpG islands of the miR-224 promoter region increased the expression of miR-224, and promoted tumor progression and metastasis of NSCLC by targeting SMAD4 and TNFα-induced protein 1 (TNFAIP1)." (PMID 33898432, 2021). "In the current study, methylation SMAD4 pattern was significantly correlated with CA15.3, tumor stage and grade, and lymph node." (PMID 33825073, 2021). "While the tumor suppressors DCC and SMAD4 have been nominated as possible drivers of this event through haploinsufficiency, more work is needed to fully understand the role of chr18 loss in SI-NET30,31." (PMID 34737276, 2021).
tumor (continued). "A potential mechanism is that HAPLN1 regulates tumor cell proliferation via the TGF-β (Smad2/3, p-Smad2/3, and Smad4) signaling pathway." (PMID 34966673, 2021). "Smad2, Smad3, Smad4, and COL1A1 proteins were strongly expressed in tumor tissues from CRC patients compared with normal colon controls." (PMID 34966673, 2021). "In conclusion, the overexpression of LAMC1, upregulated by TGFβ1 via SMAD4/SP1 synergistic activation, promoted the proliferation and migration of tumor cells mainly via NF‐κB/MMP9‐MMP14." (PMID 34218518, 2021). "Smad4 belongs to the Smad gene family, acts as a mediator of TGF-β signaling pathways, and was classified as a tumor suppressor gene which plays important roles in maintaining tissue homeostasis and suppressing tumorigenesis." (PMID 34307117, 2021). "The present results show that the tumor tissues of TNBC mice treated with a combination of low-dose Avastin and FO with Se have significantly lower levels of Smad2/Smad3 phosphorylation, Smad4, and TMEPAI than those of mice treated with Avastin alone." (PMID 33805447, 2021). "Early in tumour development, in a wild-type SMAD4 context, BMP signalling functions as a tumour suppressor, inhibiting Wnt activity but also suppressing stemness genes independently of Wnt/β-catenin." (PMID 33673710, 2021). "Moreover, SMAD4 serves as the central mediator TGF-β signaling, and its mutation plays an important initiating role by disrupting DNA damage response and repair mechanisms and enhancing genomic instability, suggesting its distinct roles in different tumor types." (PMID 34490033, 2021). "Previous reports have shown the tumor suppressive roles of DACH1, PCDH10 and SMAD4 in tumorigenesis 24-26." (PMID 33867818, 2021). "As the TGF-β cascade has a crucial role in tumor metastasis, we investigated the expression levels of its downstream effectors (i.e., SMAD2, SMAD4) in BCs using different public BC datasets." (PMID 33426510, 2021). "SMAD4 was sieved to further investigate luciferase reporter assays and RIP assays, which was investigated as a tumor suppressor in ESCC." (PMID 33869216, 2021). "On the whole, our data suggest that NRF1 is a negative regulator of SMAD4 and can interfere with TGF-β/SMAD-induced tumor suppression." (PMID 34070531, 2021). "Here, we demonstrate that NRF1 is a novel SMAD4-binding partner and that the interaction between SMAD4 and NRF1 can repress TGF-β/SMAD4–induced tumor-suppressor functions." (PMID 34070531, 2021).